CNN3 (calponin 3)
Diseases named in the same sentence as CNN3 in open-access papers (continued):
Sharing a sentence is not in itself a finding about the gene and the disease.
leukemia (3 papers, 2022 to 2024). A malignant (clonal) hematologic disorder, involving hematopoietic stem cells and characterized by the presence of primitive or atypical myeloid or lymphoid cells in the bone marrow and the blood. "Satb1 has previously been shown to be associated with heightened hematopoietic stem cell (HSC) self-renewal, whereas the role of Tubb2a, Cnn3, Nedd4, and Cand2 in hematopoiesis and/or leukemia is poorly described." (PMID 38555405, 2024). "Colony-forming unit (CFU) assays showed a substantial reduction in leukemia cell proliferation following CNN3 knockdown compared to controls." (PMID 39555457, 2024). "Knockdown of CNN3 in leukemia cell lines led to reduced cell proliferation." (PMID 39555457, 2024).
non-small cell lung carcinoma (3 papers, 2022 to 2025). A group of at least three distinct histological types of lung cancer, including non-small cell squamous cell carcinoma, adenocarcinoma, and large cell carcinoma. "For instance, an overexpression of CNN3 suppressed the invasion and proliferation of non-small cell lung cancer cells, whereas CNN3 knockout (-/-) embryos displayed increased proliferation of neuronal precursor cells." (PMID 39851570, 2025). "Interestingly, although CNN3 is generally considered an oncogene, research in non-small cell lung cancer suggests that CNN3 expression suppresses cancer cell proliferation and metastasis, indicating that CNN3’s role in cancer progression may be context-dependent." (PMID 39555457, 2024).
sarcoma (3 papers, 2020 to 2025). A usually aggressive malignant neoplasm of the soft tissue or bone. "Calponin expression has been documented in several reports focusing on different types of sarcomas, leading to the conclusion that CNN3 is required for controlling proper contractility of the stress fiber network." (PMID 33207594, 2020). "As we only had follow-up information for some enrolled patients, the correlation between CNN3 protein levels and prognosis was analyzed based on the sarcoma gene-expression dataset available on the Gene Expression Profiling Interactive Analysis (GEPIA) database." (PMID 32667904, 2020). "Additionally, we found that CNN3 mRNA expression had a significant positive correlation with the mRNA expression of two mesenchymal markers, Snail and vimentin (VIM), and two tumor proliferation markers, MKI67 and PCNA, in sarcoma." (PMID 32667904, 2020).
astrocytoma (2 papers, 2022 to 2024). "Validation of 6 biomarkers with the highest importance score in TCGA and CGGA cohorts revealed that HS3ST1, and CNN3 were overexpressed in astrocytoma, while SLAIN1, ABTB2, TRIM67 and DRG2 were overexpressed in oligodendroglioma." (PMID 35287567, 2022).
gastric cancer (2 papers, 2017 to 2019). A primary or metastatic malignant neoplasm involving the stomach. "We demonstrate that CNN3 contributes to cell invasion and resistance to doxorubicin in gastric cancer." (PMID 30911294, 2019). "Taken together, our results suggest that CNN3 plays a key role in invasiveness and doxorubicin resistance in gastric cancer cells." (PMID 30911294, 2019). "The present study was undertaken to investigate whether CNN3 influences cancer-related phenotypes in gastric cancer." (PMID 30911294, 2019). "Depletion of CNN3 protein suppressed the invasive ability of gastric cancer cells." (PMID 30911294, 2019). "In the present investigation, miR-1 was shown to simultaneously inhibit tumor growth and metastasis of breast and gastric cancers by synchronously targeting CDK4 and TMSB4X, CNN3, TWF1, CORO1C and WASF2 genes." (PMID 28159933, 2017). "In this context, the miR-1-mediated downregulation of the TMSB4X, CNN3, TWF1, CORO1C and WASF2 genes led to the inhibition of tumor cell metastasis of breast and gastric cancers." (PMID 28159933, 2017). "The highly invasive MKN-28 gastric cancer cells were more resistant to doxorubicin than the noninvasive MKN-45 cells; however, knockdown of CNN3 expression in MKN-28 cells resensitized them to doxorubicin treatment." (PMID 30911294, 2019).
MALT lymphoma (2 papers, 2015 to 2017). An indolent, extranodal type of non-Hodgkin lymphoma composed of small B-lymphocytes (centrocyte-like cells). "CNN3 was identified the gene in tumorigenic parameter as ovarian cancer and mucosa-associated lymphoid tissue lymphoma." (PMID 24934327, 2015). "Moreover, the JMJD2C gene was also found to be translocated in mucosa-associated lymphoid tissue (MALT) lymphoma and led to rearrangements of ODZ2 (odd Oz/ten-m homolog 2), JMJD2C and CNN3 (Calponin-3), which broadened the knowledge on the genetic heterogeneity of MALT lymphomas." (PMID 29207681, 2017).
schizophrenia (2 papers, 2018 to 2023). A major psychotic disorder characterized by abnormalities in the perception or expression of reality. "In a previous microarray study that was performed within the dorsolateral prefrontal cortex of schizophrenia patients, increased expression level of Cnn3 was reported." (PMID 29962931, 2018). "However, the roles of calponin-3 in schizophrenia have not been elucidated." (PMID 29962931, 2018).
Arthritis (1 paper, 2021). Inflammation of a joint. "Third, our study did not address the assessment of joint involvement in detail, which would require future studies to clarify the correlation of serum calponin 3 levels with the prevalence of each type of joint involvement such as arthritis." (PMID 33466615, 2021).
autoimmune disease (1 paper, 2021). A disorder resulting from loss of function or tissue destruction of an organ or multiple organs, arising from humoral or cellular immune responses of the individual to their own tissue constituents. "Therefore, calponin 3 has the potential to be an autoantigen of not only these autoimmune diseases but also SSc." (PMID 33466615, 2021). "Interestingly, a recent study showed that calponin 3 was identified as a novel autoantigen, and anti-calponin 3 antibodies were detected in patients with several autoimmune diseases, such as Sjögren’s syndrome, systemic lupus erythematosus, myositis, and multiple sclerosis." (PMID 33466615, 2021).
Autoimmunity (1 paper, 2015). The occurrence of an immune reaction against the organism's own cells or tissues. "So far, we have not observed any signs of such an inhibitory function of calponin 3, and mice monitored for up to one year did not develop any signs of autoimmunity as a consequence of a putative cellular hyperactivation." (PMID 26046660, 2015).
bladder cancer (1 paper, 2021). "While CNN3, SHISA2, TMED3, SRGN were downregulated in persistently infected bladder cancer cells." (PMID 34044804, 2021).
epilepsy (1 paper, 2025). A brain disorder characterized by episodes of abnormally increased neuronal discharge resulting in transient episodes of sensory or motor neurological dysfunction, or psychic dysfunction. "For example, APBB2 was reported to be associated with aging, ZNF608 with preclinical AD, ARID4A and ARVCF with neuropsychiatric diseases, CNN3 with epilepsy, and BTBD1O with ALS." (PMID 40725187, 2025).
glaucoma (1 paper, 2019). Increased pressure in the eyeball due to obstruction of the outflow of aqueous humor. "ONH‐specific gelsolin (Gene name: GSN), prostaglandin D synthase (Gene name: PTGDS), as well as calponin (Gene name: CNN3) were reported as glaucoma ONH astrocyte markers." (PMID 31470587, 2019).
Hepatic fibrosis (1 paper, 2024). The presence of excessive fibrous connective tissue in the liver. "Furthermore, mRNA transcripts such as IARS-206, TDGF1, and CNN3-202, regulated by two or more lncRNAs, demonstrated close associations with myocardial or hepatic fibrosis." (PMID 38368363, 2024).
metastatic cancer (1 paper, 2025). A carcinoma which has spread from the original site of growth to another anatomic site. "The results showed that the expression levels of CLOCK, along with CBX5, CHN1, CNN3, FNDC1, PALLD, and SULF1, were significantly elevated in metastatic cancer tissues compared to primary cancer tissues." (PMID 41350567, 2025).
muscle atrophy (1 paper, 2025). The loss of muscle tissue due to inactivity or disease. "By highlighting its role, the findings suggest CNN3 as a potential therapeutic target for muscle atrophy and related disorders." (PMID 39851570, 2025). "Recent evidence further indicates that CNN3 levels are diminished in various muscle atrophy models, such as starvation-induced myotube atrophy in murines and tibial muscular dystrophy in humans." (PMID 39851570, 2025).
placental disorders (1 paper, 2014). "We further speculated that CNN3 expression might be altered in human placentas derived from pregnancies complicated by IUGR and preeclampsia, since these placental disorders have been described to go along with impaired trophoblast invasion." (PMID 25050546, 2014).
preeclampsia (1 paper, 2014). Preeclampsia is a hypertensive disorder of pregnancy that is characterized by new-onset hypertension with proteinuria presenting after 20 weeks of gestation, and depending on mild or severe forms may initially present with severe headache, visual disturbances, and hyperreflexia. "We therefore asked the question if the expression level of the pro-invasive factor CNN3 is altered in placentas derived from pregnancies complicated by IUGR or preeclampsia." (PMID 25050546, 2014). "Hence, we speculated that CNN3 expression might be altered in placenta samples derived from patients giving birth to IUGR babies or suffering from preeclampsia." (PMID 25050546, 2014). "Our studies show that, at least in our set of placenta samples, CNN3 expression is neither deregulated in IUGR nor in preeclampsia." (PMID 25050546, 2014). "This suggests that alterations in the CNN3 level are neither connected to the pathology of IUGR nor to preeclampsia." (PMID 25050546, 2014).
spina bifida (1 paper, 2024). A congenital neural tube defect in which vertebrae are not fully formed. "Another proteomics study identified Crpm-4, Hsp-70, and calponin-3 functioning in apoptosis, folding, signal transduction, transcription, and protein synthesis that could be used as a future diagnosis and treatment methods for spina bifida." (PMID 38544816, 2024).
tumor (14 papers, 2015 to 2025). "Correlation analysis revealed that CNN3 was associated with inflammatory and immune activities, tumor microenvironment, and immune checkpoint molecules." (PMID 34797350, 2021). "The associations between CNN3 and six immune cell types including tumor-associated macrophages (TAMs), CD8+ T cells, regulatory T cells (Tregs), natural killer (NK) cells, myeloid-derived suppressor cells (MDSCs) and neutrophils were investigated." (PMID 34797350, 2021). "We also found that high CNN3 expression was associated with tumor size, tumor stage, and lymph node and distant metastases." (PMID 32667904, 2020). "Furthermore, we found that high CNN3 expression is associated with tumor size, tumor stage, lymph node metastasis, and distant metastasis." (PMID 32667904, 2020). "It was indicated that the expression levels of CNN3 were related to the clinicopathological features including age, gender, histological type, WHO grade, IDH mutation, KPS, tumor status and vital status." (PMID 34797350, 2021). "Tumor growth curves also revealed that CNN3 silencing can suppress the growth of subcutaneous tumors." (PMID 32667904, 2020). "Since cell migration is an essential step in tumor invasion and metastasis, it is possible that increased CNN3 expression can promote invasion of cancer cells by reorganization of the actin cytoskeleton or by activation of other molecules." (PMID 30911294, 2019). "As it shows, high CNN3 expression is significantly relevant to age (P < .001), gender (P = .03), WHO grade (P < .001), histological type (P < .001), IDH mutation (P = .002), KPS (P = .01), tumor status (P < .001) and vital status (P < .001)." (PMID 34797350, 2021). "Moreover, western blotting was performed to evaluate the effect of CNN3 silencing on the expression of tumor metastasis-related proteins." (PMID 32667904, 2020). "In addition, xenografted tumours, established from SiHa cells with CNN3 knockdown, displayed decreased growth and metastasis in vivo." (PMID 32051425, 2020). "In addition, CNN3 may contribute to the initial dissemination of tumor cells by downregulating the adhesion molecule E-cadherin in the primary tumor." (PMID 35008221, 2021). "Moreover, CNN3 silencing inhibited subcutaneous tumor growth and lung metastases in vivo." (PMID 32667904, 2020). "Furthermore, CNN3 silencing also inhibited subcutaneous tumor growth and lung metastasis in vivo." (PMID 32667904, 2020). "Thus, CNN3 contributes to tumor progression by inducing multiple changes in cellular physiology." (PMID 30911294, 2019). "miR-1 acts as a tumor suppressor, promoting the inhibition of tumor growth and acting with multiple target genes, such as CDK4, TMSB4X, WASF2, TWF1, CNN3, and CORO1C which are genes involved in cell cycle and metastasis." (PMID 38813102, 2024). "High CNN3 expression level was related to older age (P < .001), male (P = .048), higher tumor grade (P < .001), lower KPS score (P = .018), and status of with tumor (P < .001)." (PMID 34797350, 2021). "Among all genes in the focal amplifications, only five (TBX15, NOTCH2, PTGFRN, CNN3, and PHGDH) showed appreciably higher expression levels than those observed in tumor samples from the TCGA database." (PMID 28977029, 2017). "The sizes of xenografted tumours generated from cells with CNN3 knockdown were significantly smaller than those from cells without CNN3 knockdown." (PMID 32051425, 2020).
cancer (10 papers, 2017 to 2025). A tumor composed of atypical neoplastic, often pleomorphic cells that invade other tissues. "Our analysis and experimental results consistently suggest CNN3’s potential oncogenic role in cAML and its ability to provide survival advantages to cancer cells." (PMID 39555457, 2024). "As an important mechanism in cancer progression, we identified CNN3 as a key cuproptosis-related signature affecting cAML development." (PMID 39555457, 2024). "CNN3 plays a pivotal role in promoting the migration of cancer cells, skin cells, and trophoblast invasion." (PMID 34305633, 2021). "To determine the effect of CNN3 depletion on cancer cell invasion, we performed an in vitro two-chamber invasion assay." (PMID 30911294, 2019). "CNN3 expression was markedly elevated in highly invasive cancer cell lines compared to less invasive or noninvasive cancer cell lines." (PMID 30911294, 2019). "The TMSB4X, CNN3, TWF1, CORO1C and WASF2 genes encode cytoskeletal proteins related to actin filament dynamic regulation, and they are involved in cancer metastasis." (PMID 28159933, 2017). "Furthermore, the overexpression of CNN3 in CC cells plays a role in stimulating the growth and metastasis of the cancer." (PMID 40771905, 2025). "CNN3 is highly expressed in the brain, cancers, smooth muscle, and human placenta cytotrophoblasts." (PMID 34305633, 2021). "However, the role of CNN3 in cancer cell invasion and resistance to chemotherapeutic agents has not yet been investigated." (PMID 30911294, 2019). "In this context, molecular targeting of CNN3 may not only prevent the seeding of GC cells to other organs but also sensitize cancer cells to chemotherapy, thereby preventing the spread of GC." (PMID 30911294, 2019). "Thus, CNN3 is thought to play a pivotal role in activation of signaling molecules related to the migration of cancer cells." (PMID 30911294, 2019). "In an effort to determine whether CNN3 expression is associated with invasive properties of GC cell lines, we assessed the effects of CNN3 depletion on cancer cell migration and invasion in MKN-28 cells." (PMID 30911294, 2019). "Thus, we examined whether CNN3 expression is elevated in highly invasive cancer cell lines compared to the less or noninvasive cancer cell lines of the same cancer type." (PMID 30911294, 2019). "These genes—Derlin1, ZEB1, CNN3, and PSMD10 (gankyrin)—were selected based on previous reports of their overexpression in CC and their established roles in cancer progression, metastasis, and immune regulation." (PMID 40771905, 2025).
infection (3 papers, 2012 to 2020). The state of being infected such as from the introduction of a foreign agent such as serum, vaccine, antigenic substance or organism. "In addition, the downregulation of TUBD1 and microfilament-associated protein CNN3 associated with the cytoskeleton was detected in DT40 cells following vvIBDV infection, as also observed in CEF cells." (PMID 28086922, 2017).
CNN3 also shares sentences with these, for which no sentence is quoted: lymph node metastasis (3 papers); colon cancer (2); ovarian carcinoma (2); acute myelocytic leukemia (1); angiosarcoma (1); Arthralgia (1); autism (1); cardiac sarcomas (1); glioblastoma (1); hepatocellular carcinoma (1); lung carcinoma (1); melanoma (1); multiple sclerosis (1); myositis (1); oligodendroglioma (1); psychiatric disorder (1); Sjögren’s syndrome (1); systemic lupus erythematosus (1); systemic sclerosis (1); thyroid tumor (1).